PDE2A (phosphodiesterase 2A)
Description:
cGMP-activated cyclic nucleotide phosphodiesterase with a dual-specificity for the second messengers cAMP and cGMP, which are key regulators of many important physiological processes. Has a higher efficiency with cGMP compared to cAMP. Plays a role in cell growth and migration. [Isoform PDE2A2]: Regulates mitochondrial cAMP levels and respiration (By similarity). Involved in the regulation of mitochondria morphology/dynamics and apoptotic cell death via local modulation of cAMP/PKA signaling in the mitochondrion, including the monitoring of local cAMP levels at the outer mitochondrial membrane and of PKA-dependent phosphorylation of DNM1L.
Synonyms: CGS-PDE; cGSPDE; IDDPADS; PDE2A1; PED2A4
Tractability: Small molecule: an approved drug acts on it; a structure with a bound ligand is known; a high-quality ligand is known; it has a high-quality binding pocket; it belongs to a druggable protein family. Antibody: UniProt places it where antibodies can reach, with high confidence; its Gene Ontology location is reachable by antibodies, with high confidence. PROTAC: ubiquitination databases record sites on it; its protein half-life has been measured; a small molecule that binds it is known.
Target class: Enzyme; Phosphodiesterase; Phosphodiesterase 2; Phosphodiesterase 2A
Chemical probes: BI-1960 (high quality), CHEMBL2381188, JNJ-54082730 (high quality)
Gene: Protein-coding gene on chromosome 11 (72,576,141 to 72,674,591, reverse strand). Ensembl gene ENSG00000186642.
Subcellular location: Cell membrane (Isoform PDE2A3); Mitochondrion matrix (Isoform PDE2A2); Mitochondrion inner membrane; Mitochondrion outer membrane; Cytoplasm (Isoform PDE2A1); Mitochondrion (Isoform 5)
Subcellular location (Human Protein Atlas): Cytosol
Pathways (Reactome):
Hemostasis: cGMP effects
Signal Transduction: G alpha (s) signalling events
Gene Ontology:
Molecular function: 3',5'-cGMP-stimulated cyclic-nucleotide phosphodiesterase activity; 3',5'-cyclic-AMP phosphodiesterase activity; 3',5'-cyclic-GMP phosphodiesterase activity; 3',5'-cyclic-nucleotide phosphodiesterase activity; cAMP binding; cGMP binding; magnesium ion binding; phosphate ion binding; protein binding; protein homodimerization activity; TPR domain binding; zinc ion binding; identical protein binding; phosphoric diester hydrolase activity
Biological process: adenylate cyclase-inhibiting G protein-coupled receptor signaling pathway; cellular response to 2,3,7,8-tetrachlorodibenzodioxine; cellular response to cAMP; cellular response to cGMP; cellular response to macrophage colony-stimulating factor stimulus; cellular response to transforming growth factor beta stimulus; cGMP catabolic process; negative regulation of adenylate cyclase-activating G protein-coupled receptor signaling pathway; negative regulation of transcription by RNA polymerase II; negative regulation of vascular permeability; positive regulation of vascular permeability; aorta development; cellular response to mechanical stimulus; establishment of endothelial barrier; heart valve development; negative regulation of cAMP/PKA signal transduction; negative regulation of receptor guanylyl cyclase signaling pathway; positive regulation of gene expression; positive regulation of inflammatory response; regulation of mitochondrion organization; ventricular septum development; cyclic nucleotide catabolic process; cyclic purine nucleotide metabolic process; purine ribonucleotide catabolic process; signal transduction
Cellular component: cytoplasm; cytosol; mitochondrial inner membrane; mitochondrial outer membrane; nucleus; perinuclear region of cytoplasm; plasma membrane; endoplasmic reticulum; Golgi apparatus; mitochondrial matrix; presynaptic membrane; synaptic membrane; mitochondrion
Genetic constraint (gnomAD): Loss-of-function variants: 42 observed, 96.37 expected, observed/expected ratio (o/e) 0.44, 90% interval 0.34 to 0.56. The upper end of that interval is the gene's LOEUF score, 0.56, which puts it in group 2 of 6, group 1 being the genes least tolerant of losing a copy. Missense variants: 726 observed, 1,073.7 expected, observed/expected ratio (o/e) 0.68, 90% interval 0.63 to 0.72. Synonymous variants: 456 observed, 438.63 expected, observed/expected ratio (o/e) 1.04, 90% interval 0.96 to 1.12.
Homologues: Orthologues: chimpanzee PDE2A (100% identical), dog PDE2A (95% identical), mouse Pde2a (93% identical), rabbit PDE2A (91% identical), pig PDE2A (91% identical), guinea pig PDE2A (90% identical), rat Pde2a (89% identical), tropical clawed frog pde2a (74% identical), Drosophila melanogaster Pde11 (27% identical), Caenorhabditis elegans pde-2 (27% identical), zebrafish pde2a (9% identical). Paralogues in human: PDE11A (27% identical), PDE10A (26% identical), PDE5A (25% identical), PDE6B (23% identical), PDE6A (21% identical), PDE6C (21% identical), PDE3A (16% identical), PDE8A (15% identical), PDE3B (15% identical), PDE8B (14% identical), PDE4A (14% identical), PDE4D (14% identical), and 8 more.
Diseases named in the same sentence as PDE2A in open-access papers:
PDE2A is named in the same sentence as 110 diseases in open-access papers, as found by Europe PMC text mining. Sharing a sentence is not in itself a finding about the gene and the disease. The quoted sentences say what the papers report.
glioma (8 papers, 2021 to 2025). A benign or malignant brain and spinal cord tumor that arises from glial cells (astrocytes, oligodendrocytes, ependymal cells). "The differential expression analysis results showed that the mRNA expression levels of FXYD1, ZCCHC12, and PDE2A were highly expressed in normal brain tissues, while the other six genes were significantly upregulated in glioma samples." (PMID 41438761, 2025). "PDE2A was demonstrated to correlate with tumorigenesis in osteosarcoma and colorectal cancer and to correlate with cancer stem cell stemness in glioma and HCC." (PMID 37622118, 2023). "In glioma, PDE2A/miR-139 suppressed Wnt/β-catenin signaling by inhibiting cAMP accumulation and Glycogen Synthase Kinase-3β phosphorylation, thereby modulating the self-renewal of glioma stem cells." (PMID 37622118, 2023). "Our results demonstrated that a higher expression level of PDE2A was correlated with better overall survival and less immune infiltration in glioma." (PMID 36438805, 2022). "We further analyzed the relationship between PDE2A and miR-139 expression and glioma patient survival time." (PMID 34512162, 2021). "Expectedly, targeted overexpression miR-139 or PDE2A in glioma with OCP system significantly repressed the stemness and decelerated glioma progression." (PMID 34512162, 2021). "OX26/CTX-conjugated PEGylated liposome (OCP) was constructed to deliver miR-139 or PDE2A into glioma tissue specifically." (PMID 34512162, 2021). "Among these GSC suppressors, PDE2A was the host gene of miR-139, which was also downregulated in GSCs and inhibited glioma progression." (PMID 34512162, 2021). "Both PDE2A and miR-139 indicated better prognosis of gliomas and were inversely correlated with GSC stemness." (PMID 34512162, 2021). "The results suggested that patients with high expression of both PDE2A and miR-139 presented the best prognosis, and lower levels of both genes predicted a poor prognosis for gliomas." (PMID 34512162, 2021). "The PDE2A- or miR-139-positive rate in normal tissue was much higher than that in adjacent tumors or gliomas." (PMID 34512162, 2021). "We examined the concentration of cAMP in gliomas when PDE2A was overexpressed and found that PDE2A greatly reduced cAMP generation." (PMID 34512162, 2021). "PDE2A, which is the host gene of miR-139, shared a strong positive correlation with miR-139 expression in glioma tissues." (PMID 34512162, 2021). "Next, we examined the cAMP concentration and target gene levels in PDE2A- and miR-139-overexpressing gliomas." (PMID 34512162, 2021). "PDE2A immunofluorescence staining combined with miR-139 in situ hybridization was performed in normal, adjacent and glioma sections from glioma patients." (PMID 34512162, 2021). "PDE2A is involved in glioma stem cells (GSCs) stemness and tumorigenesis." (PMID 38324550, 2024). "Our results suggested that overexpression of both miR-139 and PDE2A could repress Wnt/β-catenin signaling significantly and reduced the stemness maintenance and tumorigenesis of gliomas." (PMID 34512162, 2021). "Additionally, the activation of Wnt/β-catenin signaling was suppressed in both PDE2A- and miR-139-overexpressing gliomas." (PMID 34512162, 2021). "Considering that Notch1 is a target of miR-139, we overexpressed miR-139 in glioma cells and found that miR-139 increased the expression of the host gene PDE2A and pre-miR-139, suggesting that miR-139 could amplify its own expression." (PMID 34512162, 2021). "Furthermore, the mRNA levels of PDE2A and miR-139 in glioma tissues were consistent." (PMID 34512162, 2021). "In our study, Phosphodiesterase 2A (PDE2A) was up-regulated, a gene known to suppress Wnt/β-catenin signaling in glioma stem-like cells by modulating cAMP accumulation and GSK-3β phosphorylation." (PMID 39874307, 2025).
glioma (continued). "PDE2A levels were notably lower in adrenocortical carcinoma (ACC), acute myeloid leukemia (LAML), lower-grade glioma (LGG), ovarian serous cystadenocarcinoma (OV), testicular germ cell tumors (TGCT), and uterine carcinosarcoma (UCS) tissues relative to their corresponding normal tissues." (PMID 39699377, 2024). "And the overexpression plasmid of miR-139 and PDE2A were packaged into OCP, which could deliver DNA fragment into glioma tissue specifically." (PMID 34512162, 2021). "PDE2A and miR-139 carried by OCP were successfully overexpressed the target genes in gliomas without influence normal brain tissues." (PMID 34512162, 2021).
lung cancer (8 papers, 2014 to 2023). A malignant neoplasm involving the lung. "A previous study has demonstrated that LINC01537 was significantly associated with lung cancer survival, inhibiting tumor proliferation and metastasis, as well as enhanced cellular sensitivity to nilotinib through stabilized PDE2A protein." (PMID 36054420, 2022). "LINC01537 stabilizes PDE2A mRNA to promote its expression through RNA–RNA interaction regulating energy metabolism in lung cancer." (PMID 35935642, 2022). "We found that LINC01537 functions as a regulator of energy metabolism to suppress lung cancer development via PDE2A, underlying a mechanism that LINC01537 stabilizes PDE2A mRNA via RNA–RNA interaction." (PMID 31374807, 2019). "As EZH2 has histone methyltransferase activity with substrate specificity for H3K27 22, the effect of EZH2 knockdown on miR-139 and PDE2A expression was analyzed in lung cancer cells." (PMID 26256448, 2015). "reports that DZNep globally inhibits histone methylation and is not necessarily specific to EZH2 25, the effect of EZH2 knockdown on miR-139 and PDE2A expression was analyzed in two lung cancer cell lines." (PMID 26256448, 2015). "We found that miR-139 was epigenetically silenced with its host gene PDE2A by H3K27me3 in lung cancer cells." (PMID 26256448, 2015). "As intronic miRNAs are sometimes expressed with their host genes in a coordinated manner 20, we measured the expression of miR-139 and PDE2A in 25 lung cancer cell lines and NHBE cells." (PMID 26256448, 2015). "Most recently it was documented that miR-139 was silenced with its host gene PDE2A through histone methylation in lung cancer." (PMID 24885920, 2014). "Since LINC01537 acts as a tumor suppressor gene via interaction with PDE2A to depress tumor energy metabolism, it will be of substantial interest to use this lncRNA accompanied with other biomarkers as a tool for assessing lung cancer survival and devise drugs to target it." (PMID 31374807, 2019). "Expression of a long PDE2A transcript was detected in the brain, but not in the 25 lung cancer cell lines and NHBE cells even after 40 real-time PCR amplification cycles, suggesting that miR-139 is cosuppressed with the short PDE2A transcript in lung cancer cells." (PMID 26256448, 2015). "This H3K4me3 peak was small in lung cancer cell lines with decreased expression of PDE2A." (PMID 26256448, 2015). "To further analyze the transcriptional regulation of the short PDE2A transcript, we performed ChIP assay of NHBE cells and five lung cancer cell lines with various levels of PDE2A and miR-139 expression." (PMID 26256448, 2015). "Thus it is possible that a physical interaction between PDE2A and LINC01537 exists, which has been observed in lung cancer." (PMID 36054420, 2022). "Despite a significant correlation between the expression of PDE2A and MIR139 in lung cancer cell lines, we and other investigators have shown that miR-139-5p and/or miR-139-3p expression is not correlated to PDE2A expression levels in leukemia, gastric and colorectal cancer cells." (PMID 35269391, 2022).
Cognitive impairment (7 papers, 2018 to 2025). Abnormal cognition is characterized by deficits in thinking, reasoning, or remembering. "Pde2a+/− mice exhibit sex-dependent socio-cognitive deficits, with males showing severe impairments associated with oxidative stress, microglial activation, and altered glutamate receptor signaling, resulting in disrupted synaptic plasticity." (PMID 41155624, 2025). "Pde2a deletion in C57BL/6J mice leads to sex-dependent socio-cognitive deficits, with male Pde2a+/− mice displaying persistent social impairments and hyperactivity, while females show milder cognitive deficits emerging in adulthood." (PMID 41155624, 2025). "PDEs such as PDE2A, PDE4D, and PDE10A have been associated with multiple autism-like behaviors and cognitive deficit at different ages in mouse models." (PMID 35338117, 2022). "Pharmacological inhibition of PDE2A normalized the communicative (p < 0.01, p < 0.05), social (p < 0.001, p < 0.05), and cognitive impairment (p < 0.001) displayed by both Fmr1-Δexon 8 and VPA-exposed rats." (PMID 35338117, 2022). "Some researchers have proved that PDE2A inhibitors have the potential for the treatment of cognitive disorders." (PMID 32351997, 2020). "Indeed, the pharmacological inhibition of two PDEs (PDE2A and PDE4D) has been associated with multiple autism-like behaviors and cognitive deficit at different ages in mouse models." (PMID 33414502, 2021). "These PDE2A more generalized brain expression patterns may explain the broad neurological features (including interictal epileptic discharges and cognitive impairment) we observed in our patient in addition to his movement disorder." (PMID 29392776, 2018). "Inhibition of phosphodiesterase 2 and 4 (PDE2A and PDE4) increases the intracellular cAMP and/or cGMP levels, which may prevent Amyloid β 42 oligomers (Aβ) related cognitive impairment and dementias." (PMID 34966284, 2021).
schizophrenia (7 papers, 2017 to 2022). A major psychotic disorder characterized by abnormalities in the perception or expression of reality. "Inhibiting PDE2A improves social recognition memory, lessens social withdrawal behavior in a rodent model of schizophrenia, and rescues social deficits in Fmr1 KO animals." (PMID 34887755, 2021). "The pharmacological inhibition of PDE2A has been evaluated in preclinical studies, thus suggesting PDE2A inhibitors as a potential treatment for neurodegenerative diseases, such as Alzheimer’s disease, schizophrenia, and dementia." (PMID 31731831, 2019). "A phase I clinical trial examining a PDE2A inhibitor for the treatment of schizophrenia is currently ongoing." (PMID 28463107, 2017). "Indeed, patients with bipolar disorder, schizophrenia and major depressive disorder showed altered expression of brain PDE2A." (PMID 35338117, 2022). "Furthermore, PDE2A inhibition ameliorated social withdrawal in a rat model of schizophrenia." (PMID 35338117, 2022). "The cAMP and cGMP dual-substrate specific PDE2A enzyme is abundantly expressed in the brain, particularly in structures of the limbic system, indicating an important role in the pathophysiology of neurodegenerative and neuropsychiatric diseases like Alzheimer’s disease, schizophrenia and dementia." (PMID 33917199, 2021). "Both PDE2A and PDE10A inhibitors are being studied in the clinic as potential treatments for schizophrenia, Huntington’s disease, Parkinson’s disease, and other movement and neuropsychiatric disorders." (PMID 34335180, 2021). "Accordingly and comparable to PDE2A, PDE10A activity is related to neurodegenerative and neuropsychiatric diseases like Huntington’s disease, Parkinson’s disease, Alzheimer’s disease, dementia, schizophrenia and depression." (PMID 33917199, 2021).
Chorea (6 papers, 2018 to 2025). Chorea (Greek for 'dance') refers to widespread arrhythmic involuntary movements of a forcible, jerky and restless fashion. "PDE2A encodes the phosphodiesterase 2A protein, and its mutations are associated with movement disorders in humans, such as chorea and paroxysmal dyskinesia." (PMID 36611792, 2023). "Biallelic LOF variants in phosphodiesterase 2a, cGMP-stimulated (PDE2A) is a newly reported gene associated with paroxysmal dyskinesia with developmental delay, chorea, ID and epilepsy." (PMID 34177764, 2021). "It has been suggested that the high expression of PDE2A in extra‐striatal brain regions might account for the presence of additional neurological signs, beyond chorea." (PMID 40492975, 2025). "The indication that PDEs are intimately involved in the pathophysiology of different movement disorders further stems from recent discoveries that mutations in genes encoding different PDEs, including PDE2A, PDE8B, and PDE10A, are responsible for rare forms of monogenic parkinsonism and chorea." (PMID 34155691, 2021).
major depressive disorder (6 papers, 2017 to 2023). An episode of depression lasting two or more weeks without an intervening episode of mania. "The positive effect of PDE2A inhibitors on depression/anxiety-like behaviours has been linked to their anti-apoptotic effects." (PMID 28463107, 2017). "PDE2A mRNA expression dysregulation has been observed in the brain regions associated with the pathophysiology of bipolar disorder (BD), major depressive disorder (MDD), and schizophrenia (SCZ)." (PMID 37605207, 2023). "The most commonly characterized selective Pde2a inhibitor, namely Bay 60–7550, generates antidepressant efficacy in the depression animal model." (PMID 35111057, 2021). "This study suggests that Gad2, Vamp2, and Pde2a are potentially involved in depression remission treated by Chaihu-Shugan-San." (PMID 35111057, 2021). "Our data show that Chaihu-Shugan-San treats depression potentially via influence 110 DEPs (Gad2, Vamp2, Pde2a, etc.), and neurotransmitters release and transmission cycle (e.g., GABA, glutamate, serotonin, norepinephrine, dopamine, and acetylcholine)." (PMID 35111057, 2021). "Pde2a inhibitor had significant neuroprotective effects on depression by affecting the cGMP and cAMP signalling pathways, contain increasing the ratio of the expression of pCREB/CREB and BDNF." (PMID 35111057, 2021). "Patients with bipolar disorder showed reduced PDE2A mRNA levels in the hippocampus, caudal entorhinal cortex, and striatum, while patients with SCZ, bipolar disorder, and major depressive disorder (MDD) showed reduced PDE2A mRNA levels in the amygdala." (PMID 33414502, 2021). "Consistent with its potential role in psychiatric diseases, Rhes also interacts with striatal proteins, such as PDE2A (phosphodiesterase 2A) and LRRC7 (leucine-rich repeat–containing 7), reported to be associated with major depression and BD." (PMID 28742811, 2017). "A study showed Pde2a mRNA expression increased in the depression cell model." (PMID 35111057, 2021). "Pharmacological inhibition of PDE2A in animal models has been shown to have beneficial effects in a number of conditions, such as cardiac hypertrophy, pulmonary hypertension as well as depression, anxiety and cognition deficits in Alzheimer’s disease." (PMID 28463107, 2017).